GRM1 (glutamate metabotropic receptor 1)
Diseases named in the same sentence as GRM1 in open-access papers (continued):
Sharing a sentence is not in itself a finding about the gene and the disease.
melanoma (continued). "The rationale for using riluzole in preclinical studies and melanoma patient trials derived from compelling evidence that the metabotropic glutamate receptor 1 (GRM1), one of the glutamate receptors, was able to induce melanoma in transgenic mice." (PMID 23077590, 2012). "The oncogenic activities of mGluR1 expressing melanoma cells are independent of BRAF and NRAS mutations; additionally it has been found that a polymorphism in the GRM1 gene is predominately found in non-CSID melanoma patients." (PMID 34359771, 2021). "We and others have shown that our Grm1-driven spontaneous melanoma prone mice develop both cutaneous and non-cutaneous melanoma." (PMID 34359771, 2021). "We conclude that the tg(Grm1)EPv melanoma mouse model does not respond to monotherapy with PD-L1 blockade and that additional mechanisms limit the antitumor immune response in these tumors." (PMID 33408092, 2021). "We demonstrated earlier that mGluR5 is not required for the oncogenic activities of Grm1 mediated transformation of melanocytes into malignant melanoma." (PMID 34359771, 2021). "Here, a significantly enhanced Grm1 expression at the age of 77d was observed in lymph nodes of the Cyld−/− mice whereas no melanoma cells were detected in Cyld+/+ mice." (PMID 31591386, 2019). "The transfection of GRM1 cDNA into the C81-61 non-tumorigenic melanoma cell line results in its transformation into an aggressive, tumorigenic cell line." (PMID 29416686, 2018). "We also tested the effects of exosomes from GRM1 expressing melanoma cells on growth, migration and invasion of GRM1 negative cells." (PMID 29416686, 2018). "The first involved the introduction of exogenous human GRM1 cDNA into an early stage melanoma cell line, C81-61, which does not express endogenous GRM1." (PMID 29416686, 2018). "If BRafV600E is turned on first, Grm1 expression can be induced, but this is not sufficient to result in development of melanoma; the cells undergo senescence." (PMID 29464040, 2018). "While others have found correlations between riluzole-induced DNA damage and GRM1 expression in melanoma cell lines, there was no apparent correlation between GRM1 level and drug response to riluzole in these breast cancer cell lines." (PMID 28591718, 2017). "Similar in vitro observations, including enhancement of Wnt/β-catenin signaling, were also reported when melanoma cells were treated with the non-competitive GRM1 antagonist, BAY 36–7620." (PMID 25915038, 2015). "In addition, the glutamate release inhibitor riluzole inhibits metabotropic glutamate receptor 1 (GRM1), blocking the MAPK pathway, which is a crucial signaling pathway controlling the pathogenesis of melanoma." (PMID 23381931, 2013). "It has previously been demonstrated that ectopic expression of GRM1 in melanocytes leads to transformation of melanocytes in vitro and tumorigenesis in vivo, and that GRM1 is strongly expressed in a majority of human melanoma cell lines and biopsies, but not in normal melanocytes." (PMID 37036756, 2023). "Additionally, in human melanoma biopsies and cell lines, but not in benign tissues and melanocytes, expression of GRM1 (mGluR1) was detected." (PMID 36457557, 2022). "Expression of GRM1 occurs in 60% of human melanomas and cytoplasm but not in benign or normal human melanocytes, suggesting that GRM1 may be involved in melanoma formation." (PMID 34360837, 2021). "Exogenous GRM1 was introduced into human melanoma cell lines with either modest GRM1 expression or absence of detectable GRM1 expression, and showed that enhanced GRM1 expression levels led to upregulated angiogenesis and increased tumorigenesis in vitro and in vivo." (PMID 29416686, 2018). "Cultured cells derived from metastatic human melanoma such as C8161 and UACC903 show elevated basal levels of activated phospho-ERK [pERK] and phospho-AKT [pAKT] compared to Grm1-negative human primary melanoma line, C81-61, and other normal human melanocytic cell lines." (PMID 29464040, 2018).
melanoma (continued). "Moreover, both heightened NFκB signaling and increased GRM1 expression, which foster glutamate-mediated MAPK-driven melanoma cell survival and the AKT–mTOR–HIF1 pathway, have been shown to support melanoma-associated proangiogenic signaling, thereby favoring melanoma growth and dissemination." (PMID 27896217, 2016). "Interestingly, we also demonstrate riluzole induced Smad linker phosphorylation in the GRM1 negative UACC930 melanoma cell line (this line does not express GRM1 because of a truncation mutation [S. Chen, personal communication])." (PMID 23077590, 2012). "Furthermore, the reduction of glutamate release induced by gabapentin might modulate the occupancy of the metabotropic glutamate receptor 1 (GRM1), as well as the NMDA receptor, which seems to induce spontaneous melanoma development in vivo and melanoma growth." (PMID 34575835, 2021). "In addition, qRT-PCR analyses revealed a comparable Grm1 mRNA expression level of cultivated Tg(Grm1) cell lines to murine cerebellum (positive control, set as 1), whereas the murine B16 melanoma and melanocytic Melan-A cell line (negative control) displayed extremely low Grm1 expression." (PMID 31591386, 2019). "Our melanoma-prone Grm1 transgenic mouse models (TG-3 and EPv) do not harbor a BRAFV600E mutation (unpublished data), which is consistent with our in vitro cultured cell studies, that introduction of exogenous Grm1 cDNA into melan-a cells (MASS clones) did not induce mutation of BRaf." (PMID 29464040, 2018). "However, GRM1 agonist, L-quisqualate, was the only compound tested that lowered xCT expression in melanoma cells (data not shown) suggesting that other possible effectors of xCT may be present other than GRM1 such as GRM5 or AMPA receptors." (PMID 30425240, 2018). "We also demonstrate that riluzole-induced Smad linker phosphorylation is independent of the expression of the metabotropic glutamate receptor 1 (GRM1), which is one of the glutamate receptors whose involvement in human melanoma has been documented." (PMID 23077590, 2012).
cerebellar ataxia (55 papers, 2012 to 2026). A neurological syndrome characterized by clumsy and uncoordinated movement of the limbs, trunk, and cranial muscles. "Other than spinocerebellar ataxia, there are published data on the GRM1 variants associated with increased risk of autism, schizophrenia, bipolar disorder, and attention deficit hyperactivity disorder." (PMID 40858856, 2025). "Another study reported that mutations in the GRM1 gene encoding mGluR1 caused progressive cerebellar ataxia." (PMID 40771880, 2025). "While the primary reported phenotype associated with the GABA and ionotropic glutamate receptor genes are epileptic and/or developmental encephalopathy, GRM1-associated disease results in spinocerebellar ataxia and other aberrations of movement." (PMID 37234784, 2023). "Novel mutations in the GRM1 gene, which encodes for mGluR1, also reportedly caused progressive forms of cerebellar ataxia in five affected families in Italy." (PMID 37139064, 2023). "Whilst mutation of GRM1 is relatively rare, dysfunction of mGluR1 and other downstream components of the mGluR1signalling pathway have previously been associated with spinocerebellar ataxias." (PMID 32765211, 2020). "Retrotransposon insertion within the gene encoding glutamate receptor, metabotropic 1 (GRM1) has been associated with neonatal cerebellar ataxia in the Coton de Tulear dog." (PMID 23741357, 2013). "Interestingly, both gain and loss-of-function mutations in GRM1 have been described in cerebellar ataxias." (PMID 37476399, 2023). "These are plausible candidate genes since Grm1 is a known mouse ataxia gene, and Cacna1e encodes a subunit of an R-type calcium channel, while mutations to the related protein family member Cacna1a, encoding a subunit of an L-type calcium channel, causing spinocerebellar ataxia." (PMID 23028291, 2012). "How YY1 and GRM1 haploinsufficiency leads to inherited cognitive impairment and spinocerebellar ataxia visible from birth is currently unknown." (PMID 41902692, 2026). "The Grm1–PKC cascade requires binding to DAG and Ca2+ is key in PC development; PKC-deficient mice showed increased intracellular Ca2+ level and LTD (long-term depression) due to AMPA transporter internalization and ataxia." (PMID 40650037, 2025). "A key, known ataxia gene is Atcay (ataxia, cerebellar, Cayman type homolog (human)), and in the cerebellum-specific network, two of its top interactors are Cacna1e (with connection confidence 0.943, ranked 18) and Grm1 (0.902, ranked 46)." (PMID 23028291, 2012). "Sequencing analysis carried out in families affected by forms of congenital cerebellar ataxia have identified splicing mutations of the GRM1 gene, which result in aberrant transcripts encoding nonfunctional mGlu1." (PMID 29760657, 2018). "However, in the global network these interactions are much weaker (0.647 for Cacna1e and 0.763 for Grm1 respectively), and would not be identified in the top 100 connections of Atcay, which supports the utility of tissue-specific networks relevant to ataxia to identify candidate genes." (PMID 23028291, 2012).
schizophrenia (37 papers, 2011 to 2025). A major psychotic disorder characterized by abnormalities in the perception or expression of reality. "A study has found that there are multiple non-synonymous single nucleotide polymorphisms (SNPs) associated with schizophrenia in the human gene encoding mGluR1 (GRM1)." (PMID 39858450, 2025). "Rare mutations in GRM1 (encoding mGlu1) have been identified in a few cases of schizophrenia, indicating their potential roles." (PMID 40362567, 2025). "Genome-wide association studies identified 12 rare deleterious mutations in the GRM1 gene, and those mutations associated with schizophrenia also reduced mGluR1 signaling." (PMID 33918323, 2021). "The mechanisms through which mGlu1 receptors regulate mPFC interneurons are especially interesting in light of human genetic studies revealing multiple loss-of-function mutations in the human mGlu1 gene, GRM1, associated with schizophrenia." (PMID 34731619, 2021). "Two recent independent studies have identified 12 rare deleterious nonsynonymous single nucleotide polymorphisms in the GRM1 gene encoding for mGlu1 in schizophrenia." (PMID 28446243, 2017). "GRM1 encodes the metabotropic glutamate receptor 1 (mGluR1), whose documented role as a modulator of neuronal signalling and synaptic plasticity makes it a plausible schizophrenia candidate." (PMID 22448230, 2012). "GRM1 regulates the calcium levels of the postsynaptic cytosol as a G protein-coupled neurotransmitter receptor, whose mutations mainly result in schizophrenia and bipolar disorder, and has been regarded as a potential novel drug target for refractory epilepsy therapy." (PMID 37047373, 2023). "Therefore, enhancing mGlu1 signaling through selective agents has the potential to rescue deficits in schizophrenia patients with deleterious GRM1 mutations." (PMID 28446243, 2017). "Interestingly, recent studies reveal that GRM1 mutations associated with schizophrenia reduce mGlu1 signaling in cell lines and that selective mGlu1 PAMs can partially rescue the reduction in glutamate-mediated calcium signaling in vitro." (PMID 28446243, 2017). "Deleterious mutations in the GRM1 gene have been found in patients with schizophrenia." (PMID 25950944, 2015). "GRM1 is associated with a number of neurological diseases including schizophrenia and depression and is significantly increased +1.83 fold, and HCN2, which contributes to spontaneous brain rhythmic activity, and dysfunction is associated with epilepsy, is increased +2.7 fold." (PMID 25183238, 2014). "The family segregation analysis showed that, in addition to the schizophrenia probands, GRM1 mutations (e.g. F122L, Y632H and P970L) were also present in 1st degree relatives with other neuropsychiatric conditions not limited to psychosis, suggesting a pleiotropic effect." (PMID 22448230, 2012). "The specific effect onsynaptic function that this cluster of mutations interfere with remains to beidentified, however, GRM1 plays an important role in synaptic scaling, a process that maybe abrogated in schizophrenia and perturbed by mutations in GRM1 that affectsplicing." (PMID 21559497, 2011). "In vivo study have demonstrated the coupling of glutamate metabotropic receptor 1/5 and GluD1 is essential to the firing of dopamine neurons in the midbrain that are correlated with the physiopathology of schizophrenia." (PMID 38075685, 2023). "In more detail, we found one Rab32 always coupled with the melanoma oncogene Grm1, while one Rab38 is always close to Grm5, a gene playing a fundamental role in many human disorders such as schizophrenia and autism." (PMID 26818140, 2016). "Here, we examined the occurrence, inheritance and functional effects of rare GRM1 nsSNPs in a clinically and neurocognitively characterised sample of 450 schizophrenia cases and 605 controls." (PMID 22448230, 2012).
schizophrenia (continued). "In this study, we performed Sanger sequencing of a single gene, GRM1, in a sample of well-characterized schizophrenia cases and controls from the West Australian Family Study of Schizophrenia." (PMID 22448230, 2012). "GRM1 identified in this association study has not previously beenlinked genetically with schizophrenia and bipolar disorder, although other evidencesupports its involvement in these and other neurological disorders." (PMID 21559497, 2011). "Furthermore, genes (including GRM1, ADK, CACNA1C, CRK and GAB1) which the most significant SNPs of the five first-generation antipsychotics specific analyses are located within were both associated with the schizophrenia and heart diseases." (PMID 35136033, 2022). "While the experimentally documented mGluR1 functions could be related to the dysfunctional glutamatergic signalling and impaired synaptic plasticity underlying the cognitive deficit of affected individuals, GRM1 has not emerged as a schizophrenia candidate gene from linkage and association studies." (PMID 22448230, 2012). "Preclinically, Grm1 knockout mice display deficits in prepulse inhibition (PPI), a behavioral assessment of sensory gating which is the process of filtering unnecessary stimuli from total sensory stimuli and which is impaired in schizophrenia patients." (PMID 28446243, 2017).
breast carcinoma (20 papers, 2013 to 2025). "Three GRM1 SNPs, rs6923492, rs362962, and rs1125462, were evaluated in the breast cancer cohort for possible associations with breast cancer phenotypes." (PMID 23922822, 2013). "As with prior studies with this cohort, associations were observed for GRM1 SNPs that were highly dependent on receptor status of the breast cancer." (PMID 23922822, 2013). "Because of the associations with estrogen receptor status, this data implicates GRM1 as having a functional role in ER+ breast cancer where its expression associates with response to tamoxifen." (PMID 23922822, 2013). "This study was undertaken to evaluate GRM1 expression and polymorphic variants in GRM1 for associations with breast cancer phenotypes." (PMID 23922822, 2013). "Three single nucleotide polymorphisms (SNPs) in GRM1 were evaluated for associations with breast cancer clinicopathologic variables." (PMID 23922822, 2013). "In summary, it was found that GRM1 expression and two polymorphic variants associate with breast cancer phenotypes." (PMID 23922822, 2013). "Three GRM1 SNPs were evaluated for associations with breast cancer clinicopathologic variables." (PMID 23922822, 2013). "The oncogenic effects of Grm1 in mammary tumors were shown using immortalized mouse mammary epithelial cells (iMMECs)." (PMID 34359771, 2021). "mGluR1 expression has been widely explored in breast cancer, supporting angiogenesis in these tumors, and silencing of this receptor (GRM1 shRNA) resulted in inhibition of cell proliferation." (PMID 28212543, 2017). "Recently, we detected metabotropic glutamate receptor-1 (gene: GRM1; protein: mGluR1) in breast cancer and found that it plays a role in the regulation of cell proliferation and tumor growth." (PMID 24633367, 2014). "Evaluation of immunohistochemical staining of GRM1 in breast cancer and correlation with molecular features from a breast tissue microarray." (PMID 23922822, 2013). "A genetic and molecular study of metabotropic glutamate receptor 1 (GRM1) in human breast cancer was conducted." (PMID 23922822, 2013). "Induced knockdown of GRM1 in an ER+ breast cancer cell line correlated with reduced cell proliferation." (PMID 23922822, 2013). "In vitro analysis showed increased GRM1 expression in breast cancer cells treated with estrogen or the combination of estrogen and progesterone, but reduced GRM1 expression with tamoxifen treatment." (PMID 23922822, 2013). "We also evaluated GRM1 expression in human breast cancer, as a function of hormonal modulation, and for its association with risk of breast cancer recurrence." (PMID 23922822, 2013). "As no further changes in GRM1 expression were observed with the addition of progesterone to breast cancer cells in vitro, estrogen appears to have the greatest effect on GRM1 expression." (PMID 23922822, 2013). "The pro-proliferative, pro-growth, and anti-apoptotic signals occurring as a result of GRM1 over-expression and activation would provide a survival advantage for GRM1-expressing breast cancer cells." (PMID 23922822, 2013). "Beyond SNP functionality, altered GRM1 expression displayed a phenotype in breast cancer cell behavior." (PMID 23922822, 2013). "GRM1 has previously been reported to play a role in breast cancer cell growth and proliferation." (PMID 28591718, 2017). "A similar study performed in women carrying breast cancer revealed a significant correlation between the GRM1 CC genotype of rs362962 and the development of hormone receptor-negative breast cancer and association of rs6923492 and rs362962 genotypes with age at diagnosis." (PMID 24610491, 2014). "Furthermore, ER+ breast cancer was also significantly more likely to be GRM1+ (p<0.002) where 83% of ER+ tumors were also GRM1+ but only 66% of ER- tumors were GRM1+." (PMID 23922822, 2013). "Additionally, induced knockdown of GRM1 in an estrogen receptor positive breast cancer cell line correlated with reduced cell proliferation." (PMID 23922822, 2013).